MRPS18A (mitochondrial ribosomal protein S18A)
Synonyms: MRP-S18-3; MRP-S18-a; S18mt-a; FLJ10548; MRPS18-3; mL66; HumanS18b; S18bmt
Tractability: Small molecule: a structure with a bound ligand is known. PROTAC: its protein half-life has been measured.
Target class: Other cytosolic protein
Gene: Protein-coding gene on chromosome 6 (43,671,202 to 43,687,800, reverse strand). Ensembl gene ENSG00000096080.
Subcellular location: Mitochondrion
Pathways (Reactome):
Metabolism of proteins: Mitochondrial ribosome-associated quality control; Mitochondrial translation elongation; Mitochondrial translation initiation; Mitochondrial translation termination
Gene Ontology:
Molecular function: small ribosomal subunit rRNA binding; structural constituent of ribosome
Biological process: mitochondrial translation; translation
Cellular component: mitochondrial large ribosomal subunit; mitochondrial small ribosomal subunit; mitochondrion; mitochondrial inner membrane; ribosome
Genetic constraint (gnomAD): Loss-of-function variants: 19 observed, 19.7 expected, observed/expected ratio (o/e) 0.96, 90% interval 0.67 to 1.41. The upper end of that interval is the gene's LOEUF score, 1.41, which puts it in group 5 of 6, group 1 being the genes least tolerant of losing a copy. Missense variants: 285 observed, 246.09 expected, observed/expected ratio (o/e) 1.16, 90% interval 1.05 to 1.28. Synonymous variants: 105 observed, 90.5 expected, observed/expected ratio (o/e) 1.16, 90% interval 0.99 to 1.36.
Homologues: Orthologues: chimpanzee MRPS18A (99% identical), macaque MRPS18A (95% identical), rabbit MRPS18A (88% identical), guinea pig MRPS18A (83% identical), dog MRPS18A (81% identical), mouse Mrps18a (81% identical), rat Mrps18a (73% identical), pig MRPS18A (71% identical), tropical clawed frog mrps18a (61% identical), zebrafish mrps18a (58% identical), Drosophila melanogaster mRpS18A (26% identical), Caenorhabditis elegans iglr-2 (12% identical), and 1 more.
Diseases named in the same sentence as MRPS18A in open-access papers:
MRPS18A is named in the same sentence as 5 diseases in open-access papers, as found by Europe PMC text mining. Sharing a sentence is not in itself a finding about the gene and the disease. The quoted sentences say what the papers report.
breast carcinoma (1 paper, 2017). "We identified the mitochondrial protein Mrps18a as being upregulated in human breast cancer cells compared to normal breast cells." (PMID 28056857, 2017). "Although the functions of this particular protein are currently unexplored both in the context of the normal cell state as well as in cancer cells, we found that the expression of Mrps18a is upregulated in breast cancer cells compared to normal cells." (PMID 28056857, 2017). "We identified the mitochondrial ribosomal protein s18a (Mrps18a) as a protein which is upregulated in breast cancer." (PMID 28056857, 2017). "This study describes the identification of Mrps18a as an antigen which exhibits increased expression by some human breast cancer cells compared to normal cells." (PMID 28056857, 2017). "In this study, we identified Mrps18a as a putative breast cancer marker using this method." (PMID 28056857, 2017). "IHC analysis showed that Mrps18a is upregulated in human breast cancer cells compared to normal cells, indicating that Mrps18a may be involved in oncogenesis." (PMID 28056857, 2017).
liver cancer (1 paper, 2021). An epithelial or non-epithelial malignant neoplasm that arises from the liver. "Similar to mS23, the upregulation of mL66 (MRPS18-A) expression can promote the development of liver cancer." (PMID 34071057, 2021).
cancer (1 paper, 2017). A tumor composed of atypical neoplastic, often pleomorphic cells that invade other tissues. "Mrps18a cannot be considered a unique biomarker for K19 and K14 positive cells, as it is found in both normal and cancer cells." (PMID 28056857, 2017). "However, Mrps18a was not homogeneously upregulated in all cancer cells, suggesting the existence of sub-populations within the tumor." (PMID 28056857, 2017). "A specific role for Mrps18a in cancer has not been identified until now." (PMID 28056857, 2017).
infection (1 paper, 2021). The state of being infected such as from the introduction of a foreign agent such as serum, vaccine, antigenic substance or organism. "Among the ribosomal proteins, Treacle ribosome biogenesis factor 1(TCOF1), nuclear transport factor 2 like export factor 2(NXT2), ribosomal protein L37(RPL37), ribosomal protein L29 (RPL29) and mitochondrial ribosomal protein S18A(MRPS18A) are all up-regulated in the early stages of infection." (PMID 34092256, 2021).
MRPS18A also shares sentences with these, for which no sentence is quoted: tumor (1 paper).